HOTAIR (HOX transcript antisense RNA)
Diseases named in the same sentence as HOTAIR in open-access papers (continued):
Sharing a sentence is not in itself a finding about the gene and the disease.
lung cancer (continued). "Overall, with the data available, HOTAIR seems to play an oncogenic role in lung cancer; however, robust mechanisms through which this lncRNA function remain to be uncovered." (PMID 37370745, 2023). "For example, lung cancer tissues exhibit elevated levels of HOTAIR and MALAT1, which can facilitate the growth, invasion, and metastasis of lung cancer." (PMID 38011277, 2023). "The high level of HOTAIR expression is related to the development, proliferation, and metastasis of lung cancer." (PMID 36361470, 2022). "In lung cancer, the lncRNA HOTAIR is involved in cigarette smoke extract (CSE)-induced carcinogenesis, and LINC01186 inhibits cancer migration and invasion through epithelial-mesenchymal transition." (PMID 35372012, 2022). "In summary, HOTAIR has become as an important novel master regulator of gene expression and lung cancer development and possesses tremendous potentials in the management of this malignancy." (PMID 34976181, 2022). "HOTAIR can regulate the resistance of lung cancer cells to DDP by reducing the expression of p21WAF1/CIP1." (PMID 35227173, 2022). "Further, miR-326 overexpression is able to reverse cisplatin chemoresistance of lung cancer cells in vitro and in vivo and this activity is strongly related to aberrant HOTAIR expression." (PMID 33540611, 2021). "The upregulation of HOTAIR was related to resistance of gefitinib through the regulating cell cycle in lung cancer." (PMID 34616670, 2021). "Bioinformatics analysis and Luciferase reporter assay identified DACH1 as a direct target of miR-217, suggesting that the HOTAIR/miR-217/DACH1 signaling pathway is strongly involved in lung cancer progression." (PMID 33540611, 2021). "Our previous report demonstrated that HOTAIR is a marker for abnormal cell cycle regulation in lung cancer." (PMID 34405017, 2021). "ChIP-PCR experiments indicate that HOTAIR increases H3K27me3 recruitment to the promoter of p16 and p21 in PC-9 lung cancer cells overexpressing HOTAIR." (PMID 34405017, 2021). "To explore the role of HOTAIR in gefitinib resistance, we upregulated HOTAIR expression in gefitinib-sensitive lung cancer PC9 cells and established HOTAIR-overexpressing cell lines." (PMID 34405017, 2021). "Until now, only a limited number of CS-associated lncRNAs have been reported in lung cancer, namely, Smoke and Cancer-associated LncRNA–1 (SCAL1), HOX Transcript Antisense RNA (HOTAIR), H19, and Metastasis-Associated Lung Adenocarcinoma Transcript 1 (MALAT1)." (PMID 33684161, 2021). "Similar to the previous studies, HOTAIR overexpression led to gefitinib resistance in lung cancer cells." (PMID 34405017, 2021). "In this regard, it was already known that HOTAIR induces chemoresistance activating Wnt pathway in other types of cancer such as ovarian, colorectal and lung cancer." (PMID 34778043, 2021). "In the present study, we revealed that HOTAIR is upregulated in gefitinib-resistant lung cancer cells and over-expression of HOTAIR enhances gefitinib resistance in lung cancer cells." (PMID 34405017, 2021). "We previously reported that HOTAIR influences cell cycle regulation and is a marker of cell cycle dysregulation in lung cancer." (PMID 34405017, 2021). "For example, knockdown of lncRNA HOTAIR has been carried out in multidrug-resistant lung cancer cell lines (H69AR and H446AR) to assess its influence on chemoresistance." (PMID 33362860, 2020). "The relationship between HOTAIR expression and the prognoses of male or female patients with lung cancer was analyzed using UALCAN software." (PMID 32394637, 2020). "In lung cancer, aberrant expression of HOTAIR correlates with advanced stage, lymph nodes metastases, and poor prognosis." (PMID 32397382, 2020). "In this study, three SNPs of HOTAIR (rs920778, rs1899663, and rs4759314) were investigated in order to explore the relationship of these SNPs with the pathogenesis of lung cancer." (PMID 32394637, 2020).
lung cancer (continued). "These lncRNAs were involved in ten treatment resistances in lung cancers, with HOTAIR being itself described in seven resistances." (PMID 32438606, 2020). "In the present study, we investigate the effect of miR-149-5p, HNRNPA1, and HOTAIR on lung cancer cells." (PMID 33102210, 2020). "For example, lncRNA HOTAIR has been reported to promote the DNA-damaging drug cisplatin resistance in part by regulating p21WAF1/CIP1 pathways in lung cancer cell lines." (PMID 32149026, 2020). "In conclusion, this is the first report demonstrating reciprocal interaction of miR‐34a‐5p‐ and HOTAIR‐mediated regulation of EMT‐associated gene expression by the combination of BBR and gefitinib in human lung cancer cells." (PMID 32248643, 2020). "Expression of HOTAIR was found to increase in a variety of cancers, including nonsmall cell lung cancer (NSCLC)." (PMID 32394637, 2020). "HOTAIR is highly expressed in various cancers, including lung cancer, and induces the proliferation and metastasis of cancer cells." (PMID 32394637, 2020). "Previous reports indicated that higher HOTAIR expression was observed in lung cancer patients with the tobacco smoking habit compared to those who did not smoke." (PMID 30813594, 2019). "Herein, we extended these studies and found that SM inhibited the growth of human lung cancer cells by suppressing PDPK1 expression through a reciprocal interaction between HOTAIR and miR‐214‐3p." (PMID 31475459, 2019). "This complex interaction of HOTAIR and miR‐214‐3p, and the regulatory feedback axis contribute to the overall anti‐lung cancer effects of SM in vitro and in vivo." (PMID 31475459, 2019). "Gong et al13 found that SNPs in HOTTIP, H19, and CCAT2 were associated with lung cancer risk, and SNPs in MALAT1, H19, CCAT2, HOTAIR, and ANRIL were related to lung cancer patients’ response to platinum‐based chemotherapy." (PMID 30980423, 2019). "Our findings indicated that both miR‐214‐3p and HOTAIR act as upstream regulators of PDPK1 gene expression in the presence of SM in lung cancer cells." (PMID 31475459, 2019). "For examples, lncRNA, HOTAIR (Hox transcript antisense intergenic RNA), was found to be up-regulated in human lung cancer tissues and promote migration and invasion of human lung cancer cell lines." (PMID 30719228, 2019). "Increasing reports showed that many lncRNAs including RMRP, PVT1, HOTAIR, HIT, and TUG1 showed disease-associated dysregulation in lung cancer." (PMID 30154938, 2018). "Recent reports had showed that many of the lncRNAs, including H19, HOTAIR, MALAT1, ANRIL, GAS5, and GAS5-AS1, were tumor-associated, especially in lung cancers." (PMID 30154938, 2018). "In lung cancer, only a small part of lncRNAs, such as H19, HOTAIR, MALAT1, ANRIL, and GAS5 have been identified to be tumor-associated especially in lung cancers." (PMID 30154938, 2018). "HOTAIR and MALAT1 probably are the two most comprehensively studied cancer related lncRNA, whose increased expression are associated with lung cancer progression, metastasis, chemo-resistance and relapse, resulting in patients’ poor prognosis and survival." (PMID 29137177, 2017). "Recent studies have suggested that many lncRNAs are of great importance in lung cancer, such as HOTAIR, NEAT1 and PVT1." (PMID 28981099, 2017). "MiR-326 reverses chemoresistance in human lung adeno-carcinoma cells by targeting specificity protein 1, and regulates cell proliferation and migration in lung cancer by targeting phox2a and is regulated by HOTAIR." (PMID 27816050, 2016). "We next examined the effects of manipulating HOTAIR level in several lung cancer cell lines including lung ADC cells H1299, PC9 and A549, and lung SCC cells H520." (PMID 26658322, 2015). "In this study, we showed that the expression pattern of HOTAIR in lung cancer tissues and analyzed its relationship to clinical pathological features." (PMID 26658322, 2015).
lung cancer (continued). "HOTAIR-mediated regulation of senescence is potentially important in lung cancer because evasion of senescence is proposed as a critical step in lung tumorigenesis." (PMID 25491133, 2014). "For example, HOTAIR is required for the expression of matrix metalloproteinases that break down the extracellular matrix to pave the path for invasion in lung cancer cells." (PMID 25491133, 2014). "Elevated expression of HOTAIR is correlated with invasion, metastasis, and poor survival in patients with lung cancer." (PMID 25491133, 2014). "HOTAIR is an appealing therapeutic target because inhibition of HOTAIR exhibits promising anti-tumor efficacy in preclinical models of lung cancer." (PMID 25491133, 2014). "The versatility of HOTAIR function in lung cancer needs to be explored with a thorough screening of HOTAIR-bound protein partners using HOTAIR as bait in lung cancer cells." (PMID 25491133, 2014). "HOTAIR can potentially regulate lung cancer through physical interactions with E3 ubiquitin ligases and their corresponding substrates." (PMID 25491133, 2014). "In lung cancer cells HOTAIR regulates genes and signaling pathways that are pivotal to differentiation, proliferation, and invasion." (PMID 25491133, 2014). "The expression of HOTAIR is elevated in lung cancer and correlates with metastasis and poor prognosis." (PMID 25491133, 2014). "HOTAIR can be explored as a biomarker in lung cancer because its elevated expression in lung tumor tissues is correlated with metastasis, drug resistance, and poor survival in patients with lung cancer." (PMID 25491133, 2014). "Another appeal of HOTAIR as a therapeutic target arises from its critical role in resistance to chemotherapy drugs in lung cancer cells." (PMID 25491133, 2014). "Despite its discovery in other types of cancer, a crosstalk between HOTAIR and miRNAs is worth exploring in lung cancer because miR-331 and miR-130a are tumor suppressors in lung cancer." (PMID 25491133, 2014). "It is also naive to conclude that PRC2, LSD1, and the newly discovered E3 ubiquitin ligases are the sole protein partners of HOTAIR to mediate its functions in lung cancer." (PMID 25491133, 2014). "To obtain comprehensive insight of HOTAIR in lung cancer, we integrate mechanistic studies of HOTAIR in other types of cancer in our review." (PMID 25491133, 2014). "Similarly, HOTAIR is also a LncRNA that plays an important role in lung cancer; it regulates gene expression by interacting with various proteins and RNAs." (PMID 41394878, 2025). "MALAT1 and HOTAIR are found expression in various tumors, including lung cancer." (PMID 38270295, 2024). "For example, CAFs secrete CCL5, which elevates HOTAIR expression in lung cancer cells." (PMID 39717771, 2024). "Taken together, HOTAIR promotes resistance to cisplatin and radiotherapy in lung cancer." (PMID 37370745, 2023). "The findings suggest that exosomal HOTAIR may contribute to the abnormal bone remodeling seen in lung cancer bone metastasis through its effects on the TGF-β/PTHrP/RANKL pathway." (PMID 38260135, 2023). "In lung cancer, HOTAIR is overexpressed and correlated with tumor metastasis and poor prognosis, which promotes proliferation, survival, invasion, metastasis, and drug resistance in lung cancer cells." (PMID 36924407, 2023). "Furthermore, a high degree of HOTAIR and MALAT1 expression is linked to unfavorable prognoses in individuals with lung cancer." (PMID 38011277, 2023). "In lung cancer, HOTAIR is an obvious indicator of cell cycle dysregulation, which can affect the EMT and β-catenin signaling pathways by inhibiting the cell cycle from G1 to S phase, and promoting the proliferation, metastasis, and invasion of NSCLC cell lines." (PMID 36924407, 2023). "Case studies demonstrate that CCDC26 and IFNG-AS1 may be new biomarkers of lung cancer, SNHG3 may associate with PDL1 for lung cancer, and HOTAIR and BDNF-AS may be potential biomarkers of neuroblastoma." (PMID 37655066, 2023).
lung cancer (continued). "For instance, HOTAIR interacts with miR-34a-5p to mediate drug sensitivity in lung cancer cells." (PMID 34976181, 2022). "HNF1A-AS1 and HOTAIR are regulators of the tumor cell cycle and progression in lung cancer." (PMID 36553216, 2022). "In addition, high expression of HOTAIR promoted cell cycle progression in gefitinib-resistant lung cancer cells." (PMID 34405017, 2021). "In lung cancer, resistance to platinum-based chemotherapeutics can, in part, be explained through modulation of DNA repair pathways and cell cycle arrest by lncRNAs such as HOTAIR and MEG3." (PMID 33803619, 2021). "We found that HOTAIR increased in nonsmall cell lung cancer, and the genotypes of rs920778 are protective factors for female patients and nonsmoking people, which are useful for screening and prognosis for lung cancer." (PMID 32394637, 2020). "In our study, we find that the overexpression of HOTAIR could promote the proliferation and overexpression of miR-149-5p could inhibit the proliferation of lung cancer cells." (PMID 33102210, 2020). "The expression of HOTAIR in lung cancer patients of different genders was also analyzed." (PMID 32394637, 2020). "This study investigated the roles of HOTAIR and its SNPs in lung cancer." (PMID 32394637, 2020). "HOTAIR was a well-known oncogenic lncRNA in human lung cancer." (PMID 33193600, 2020). "Overexpression of HOTAIR could promote the migration and invasion of lung cancer cells and improve cell proliferation ability." (PMID 33102210, 2020). "In summary, this study investigated the roles of HOTAIR and its SNPs in lung cancer." (PMID 32394637, 2020). "Also, overexpression of HOTAIR promotes the migration and invasion ability of lung cancer cells, confirmed by the wound-healing and transwell assays, which are suppressed by overexpression of miR-149-5p." (PMID 33102210, 2020). "HOTAIR can also promote lung cancer cell proliferation, and drug resistance." (PMID 32670359, 2020). "Moreover, from this list, only H19, MALAT1, HOTAIR, and GAS5 were associated with exosomes and lung cancers in our PubMed search." (PMID 32438606, 2020). "On the contrary, the treatment of lung cancer cells with an antibody against collagen I receptor lead to a decrease of HOTAIR expression, suggesting that HOTAIR expression in tumor tissues is the result of tumor cell response to collagen I, abundantly present in TME." (PMID 31072041, 2019). "We demonstrated a role of HOTAIR in the SM‐mediated inhibition of lung cancer cell growth." (PMID 31475459, 2019). "Our findings suggested that not only the regulation but also the reciprocal and physical interaction between HOTAIR and miR‐214‐3p in the presence of SM might be involved in the anti‐lung cancer effect of SM." (PMID 31475459, 2019). "Taken together, our results demonstrated that HOTAIR may be an important target of SM and that inhibition of HOTAIR is involved in the SM‐mediated inhibition of lung cancer cells." (PMID 31475459, 2019). "To further dissect the mechanism of the inhibitory effect of SM on lung cancer cells, we searched for potential miRNAs that may link HOTAIR and other target genes." (PMID 31475459, 2019). "HOTAIR was demonstrated to downregulate HOXA5 in lung cancer." (PMID 31168296, 2019). "The interplay between ECM components and HOTAIR has been also demonstrated in lung cancer cells." (PMID 31072041, 2019). "Furthermore, with regard to the up-regulation of HOTAIR in lung cancer the SNP has been reported as a region to be associated with chemotherapy response in lung cancer patients through effect on HOTAIR function or expression." (PMID 30873206, 2019). "Similarly, modulation of HOTAIR expression by ectopic expression or depletion resulted in changes in migration and invasion capacity in esophageal cancer, lung cancer cells and one bladder cancer cell line (T-24)." (PMID 25994132, 2015).
lung cancer (continued). "Here, we found that the interaction of LSH with HOTAIR might involve in lung cancer and LSH might bind to the target gene directly as a chromatin modifier." (PMID 26658322, 2015). "In summary, the tumor suppressive miRNA-mediated decay of HOTAIR, although established in other cancer types, warrants further investigation in lung cancer because let-7, miR-34, and miR-141 act as critical tumor suppressors in lung cancer." (PMID 25491133, 2014). "Moreover, HOTAIR-mediated ubiquitination and degradation of Ataxin-1 is of particular interest to lung cancer because Ataxin-1 is essential to lung alveolization." (PMID 25491133, 2014). "In addition to proliferative phenotype, HOTAIR mediates invasive phenotype of lung cancer cells through its promotion of EMT." (PMID 25491133, 2014). "HOTAIR has emerged as a novel master regulator of lung cancer." (PMID 25491133, 2014). "Undoubtedly, inhibition of either HOTAIR or EZH2 hinders progression of lung cancer." (PMID 25491133, 2014). "Moreover, HOTAIR promotes proliferation, survival, invasion, metastasis, and drug resistance in lung cancer cells." (PMID 25491133, 2014). "Furthermore, high level of HOTAIR expression was correlated with short disease-free survival in lung cancer." (PMID 24130837, 2013). "Similarly, the expression of lncRNA HOTAIR is significantly increased in lung cancer, and it can promote the transcriptional activity of β‐catenin by binding to various proteins related to the Wnt signaling pathway, such as EZH2, enhancing the oncogenic effects of the Wnt pathway." (PMID 39991629, 2025). "Similarly, the expression of lncRNA HOTAIR is significantly increased in lung cancer, and it can promote the transcriptional activity of β‐catenin by binding to various proteins associated with the Wnt signaling pathway, such as EZH2, thereby enhancing the oncogenic effects of the Wnt pathway." (PMID 39991629, 2025). "For instance, lncRNA HOTAIR has been shown to associate with DNMT1, DNMT3A, and DNMT3B, which are concentrated in the promoter regions of genes associated with tumor metastasis, resulting in hypermethylation of these genes and promoting the metastatic potential of lung cancer cells." (PMID 41394878, 2025). "HOTAIR could promote the migration, invasion ability, and cell proliferation of lung cancer cells." (PMID 33102210, 2020). "HOTAIR could also promote lung cancer cell metastasis in mice model." (PMID 30719228, 2019). "Thus, function and target of HOTAIR in lung cancer remains unclear and is investigated in the current study." (PMID 26658322, 2015). "Thus HOTAIR can promote dedifferentiation and proliferation in lung cancer." (PMID 25491133, 2014). "For certain lncRNAs closely related to lung cancer progression, such as MALAT1 and HOTAIR, small interfering RNA (siRNA) or short hairpin RNA (shRNA) can be designed to inhibit their expression, thereby affecting the biological behavior of cancer cells." (PMID 41394878, 2025). "This study aims to combine the understanding of the role of MALAT1, HOTAIR, and AFAP1‐AS1 lncRNAs in the metastasis of lung cancer by pulling the findings of the previous studies." (PMID 39725668, 2024). "The primary objective of the study was to investigate the association between the expression levels of three lncRNAs (MALAT1, HOTAIR, and AFAP1‐AS1) and lymph node metastasis (LNM) of lung cancer." (PMID 39725668, 2024). "LncRNAs have become the key regulatory factors in development and progression of lung cancer, functioning as oncogenes (e.g., MALAT1, HOTAIR, H19 and ANRIL) or tumor suppressors (e.g., MEG3, GAS5, and TUG1)." (PMID 34976181, 2022). "Overexpression of HOTAIR promotes cell cycle progression by silencing p16 and p21 cooperating with EZH2 in human drug-resistant lung cancer cells." (PMID 34405017, 2021). "The top 5 long non-coding RNAs that use the IPCARF algorithm to predict lung cancer are: GAS5,XIST,CDKN2B-AS1, PVT1 and HOTAIR." (PMID 33794766, 2021).